CCNA2 (cyclin A2)
Diseases named in the same sentence as CCNA2 in open-access papers (continued):
Sharing a sentence is not in itself a finding about the gene and the disease.
pancreatic cancer (28 papers, 2013 to 2025). "Overexpression of Roundabout homolog 1 caused S-phase arrest to inhibit pancreatic cancer cell proliferation by significantly reducing the expressions of CCNA2 and CDK2." (PMID 35246013, 2022). "Overexpression of CST1 was also correlated with malignancy-associated proteins such as PCNA, cyclin D1, cyclin A2 and cyclin E in pancreatic cancer cell line." (PMID 26569312, 2015). "After the knockdown of LSD1, it was found that the impaired expression of CCNA2 (cyclin A2) and the growth of pancreatic cancer is partially inhibited." (PMID 40028036, 2025). "In pancreatic cancer, MBOAT2 overexpression increases CDK2 and CCNA2 expression levels, causing the cell cycle to advance from the G1 to the G2 phase." (PMID 37240761, 2023). "For example, cucurbitacin I reduces the levels of p-JAK2 and p-STAT3 proteins and decreases the expression of CCND1 and CCNA2 in pancreatic cancer cells." (PMID 37958903, 2023). "Subsequently, they found that KLF14 transrepressed Cyclin A2 promoter in pancreatic cancer cell lines." (PMID 34031939, 2021). "The expression of CCNA2, CCNB1, CDC6 and GAPDH have all been implicated in various cancers, including lung, ovarian and pancreatic cancer." (PMID 32899298, 2020). "Eight genes (BUB1, BUB1B, CCNA2, CCNB2, CDC6, CDC20, CDK1, and TTK) among 21 common network genes were correlated with worse survival of pancreatic cancer, highlighted with P-value significantly <0.05." (PMID 32117719, 2020).
gastric cancer (27 papers, 2006 to 2025). A primary or metastatic malignant neoplasm involving the stomach. "CCNA2 showed a diagnostic value in differentiating gastric cancer tissues from normal gastric tissues." (PMID 40345591, 2025). "Our study suggests that CCNA2 is a novel biomarker predictive of sensitivity to PLK1 inhibitors for the treatment of advanced gastric cancer, particularly cases carrying KRAS mutation." (PMID 32486290, 2020). "Pyroptosis is also associated with gastric cancer via downregulation of GSDMD accelerating expression of cdk2/cyclin A2 complexes that promote transition from S to G2 phase, thus accelerating gastric cancer cellular proliferation." (PMID 38645692, 2024). "Our findings hold translational implications for the treatment of gastric cancer patients with aberrant upregulation of CCNA2 via synthetic lethal approaches targeting cell cycle progression." (PMID 32486290, 2020). "First, we sought to validate differential expression of cyclin A2 protein in gastric cancer cell lines selected from both sides of the drug response profile for PLK1 inhibitors." (PMID 32486290, 2020). "Further, we demonstrated that CCNA2 expression is elevated in KRAS mutant gastric cancer cell lines and primary tumors, resulting in an increased sensitivity to PLK1 inhibitors." (PMID 32486290, 2020). "Compared to resistant cells, gastric cancer cells sensitive to PLK1 inhibitors showed increased expression of cyclin A2." (PMID 32486290, 2020). "We performed pharmacogenomics analysis using a gastric cancer cell line panel and discovered a causal linkage cascade of oncogenic KRAS mutation, aberrant CCNA2 upregulation and hypersensitivity to PLK1 inhibitors." (PMID 32486290, 2020). "Taken together, we deemed that elevated CCNA2 expression is required to confer sensitivity to PLK1inhibitors in gastric cancer cell lines." (PMID 32486290, 2020). "HMGA1P4 regulates CCNA2 by miR‐301b/miR‐508 in gastric cancer." (PMID 35480884, 2022). "Poor prognosis in GC patients related with high expressions of cyclins.CCNA2 is a novel predictive biomarker of sensitivity to PLK1 inhibitors for the treatment of advanced gastric cancer, whose overexpression was an indicator of poor prognosis." (PMID 34126961, 2021). "Therefore, we decided to further investigate whether CCNA2 may be a functional of differential responses to PLK1 inhibitors in gastric cancer." (PMID 32486290, 2020). "Therefore, we hypothesized that aberrant upregulation of cyclin A2 in gastric cancer cells may elicit synthetic lethal vulnerability to PLK1 inhibition through failed cell cycle progression, particularly at the M phase." (PMID 32486290, 2020). "In addition, while depletion of mutant KRAS reversed cytotoxicity to BI-2536 and volasertib, co-expression of CCNA2 in this context was sufficient to reintroduce sensitivity, indicating that sensitivity to PLK1 inhibitors in KRAS mutant gastric cancer cells is mediated by CCNA2 upregulation." (PMID 32486290, 2020). "Previous studies have reported the differential expression of the genes we identified in gastric cancer, but few studies have reported the differential expression of AURKB, CCNA2, PLK1, TPX2, and CDK1 in gastric cancer." (PMID 37238607, 2023). "In gastric cancer (GC), pyroptosis can be inhibited by the downregulation of gasdermin D (GSDMD), which expedites the expression of Cdk2/cyclin A2 complexes." (PMID 37198617, 2023). "It was confirmed that Cyclin A2 and cyclin-dependent kinase dysregulated GSDMD through the inhibition of PI3K–AKT pathway in gastric cancer." (PMID 35154117, 2022). "GSDMD reduces the expression of Cyclin A2 and Cyclin-Dependent Kinase (CDK2) by inhibiting ERK1/2, STAT3, and PI3K/Akt in gastric cancer (GC) cells." (PMID 35963853, 2022).
gastric cancer (continued). "This disagreement may be due to forced GSDMD overexpression, which can reverse gastric cancer cell proliferation by inactivating the ERK, STAT3, and PI3K/AKT pathways, and then inhibiting the Cyclin A2/CDK-2 complex to arrest the S/G2 phase transition." (PMID 36120543, 2022).
melanoma (22 papers, 2009 to 2025). A malignant, usually aggressive tumor composed of atypical, neoplastic melanocytes. "In B16F10 melanoma cells, palbociclib decreased protein levels of cyclin A2 but increased cyclin D1 and cyclin E1 protein levels." (PMID 40904502, 2025). "The Q1 cohort demonstrated significantly elevated expression of CCNA2, CCNB1, CCND1, and CDH2, indicating CDC25A’s potential regulatory role in coordinating melanoma cell cycle progression with EMT dynamics." (PMID 40216745, 2025). "According to the RT-PCR results, CCNA2 and CCNB1 expression levels decreased across all canine melanoma cell lines, whereas CCND1 expression was notably increased." (PMID 40642276, 2025). "In human HMV-II melanoma cells, siRNA knockdown of TLE3 expression resulted in a reduction of CYCLIN A2 protein levels." (PMID 30719233, 2019). "For example, CDK1 was reported to interact with Sox2 and promote tumor initiation in human melanoma, CCNA2 and AURKA inhibitors are now available and has shown encouraging effect for treatment of melanoma." (PMID 31921860, 2019). "Receiver operating characteristic (ROC) curves showed an area under the curve (AUC) >90.0% for KPNA2, DTL, BACE2, DTYMK, E2F3 and SLC25A13, >80.0% for CCNA2, FOXM1, KIF4A, SLC45A2, COPS8, SLC45A13 and 70.0% for CDC25A and LINC00520; all significantly discriminating melanoma from benign nevi." (PMID 36320118, 2022). "Strikingly, overexpression of LINC-PINT significantly reduced melanoma cells progression via downregulating the potential target genes CDK1, CCNA2, AURKA, and PCNA through recruiting EZH2 protein, which in turn mediated the trimethylation of H3K27 of promoter regions of target genes." (PMID 31921860, 2019). "Furthermore, the expression levels of CCNA2, CCNB1, CDK1, and CDK4 decreased in melanoma cells treated with metformin, whereas the levels of p21 and CCND1 increased." (PMID 30754729, 2019).
liver cancer (21 papers, 2015 to 2025). An epithelial or non-epithelial malignant neoplasm that arises from the liver. "Studies have shown that high expression of CDK1, CCNB1, and CCNA2 is associated with reduced overall survival in patients with liver cancer." (PMID 35463358, 2022). "However, this signature was associated with CCNA2/E1 rearrangements only in liver cancer." (PMID 30531861, 2018). "In patients with liver cancer, the activation of CCNA2 promoted liver cancer cell aggressiveness, where the patients also had worse prognosis." (PMID 37504265, 2023). "The levels of CCNA2 are elevated in a variety of tumors such as breast, cervical, and liver cancers." (PMID 33968978, 2021). "Contrary to CCNA2 alterations that seem to be specific of liver cancers, CCNE1 activation by high-level amplification is frequent across human cancers, in particular in gynecologic cancers." (PMID 30531861, 2018). "Collectively, the current clinical observation and our previous report suggested that targeting the FXR/miR-22/CCNA2 axis is a potential therapeutic option to develop drugs for liver cancer therapy." (PMID 27738335, 2016). "In addition to CCNB1, CDK1, CDC45, BUB1B, and CCNA2, we also identified five hub genes in Chinese liver cancer, namely AURKA, KIF11, TOP2A, TPX2, and HMMR, which play a crucial role in regulating the cell cycle." (PMID 34257537, 2021). "CCNA2 was recognized as an effective prognostic marker in prostate, colon, lung, and liver cancers." (PMID 33879165, 2021). "CCNA2 gene was first detected in primary liver cancer cells, which appeared in the late G1 and could bind to CDK and CDK2, Respectively; it could affect the G1/ S phase and G2/M phase of the cells." (PMID 31956366, 2020). "Thus, the relationship between cyclin A2/E1 activation and signature RS1 is specific to liver cancer, and the molecular cause of this signature in other cancer types remains to be elucidated." (PMID 30531861, 2018). "qPCR validation in normal liver and HCC tissues showed that CCNA2, CSRP2, ILF2, KIF2C, RACGAP1, and VARS were significantly upregulated in the HCC group (all p-values < 0.0001), providing more evidence for their role in liver cancer progression and potential as HCC biomarkers." (PMID 41323394, 2025). "In addition, GEPIA online analysis showed that ESR1, AR, CCNB1, CDK1, AKR1C3 and CCNA2 might become potential target genes for the survival and prognosis of PADP for the treatment of liver cancer." (PMID 35463358, 2022).
non-small cell lung carcinoma (21 papers, 1997 to 2026). A group of at least three distinct histological types of lung cancer, including non-small cell squamous cell carcinoma, adenocarcinoma, and large cell carcinoma. "C2-ceramide also reduces the pro-survival proteins Akt and NFκB, causing the down-regulation of survivin and cyclin A2, which are reported to frequently overexpress in non-small cell lung cancer." (PMID 24393431, 2014). "Activation of the Rac1-P38-ATF2 signaling pathway in non-small cell lung cancer cells has been documented to upregulate the expressions of Cyclin A2, Cyclin D1, and MMP2 proteins, thus promoting tumor growth." (PMID 39633985, 2024). "DNAH17-AS1 promotes the development of non-small cell lung cancer by targeting the miR-877-5p/CCNA2 pathway." (PMID 35480884, 2022). "The combination of metformin and pemetrexed exhibited an antiproliferative effect by affecting the cell cycle in non-small-cell lung cancer via downregulation of CCNA2 and CCND1, and the upregulation of CDKN1B." (PMID 35480884, 2022). "CCNA2 promotes invasion and migration of non-small cell lung cancer cells through integrin αvβ3 signaling pathway." (PMID 31992202, 2020). "In non-small-cell lung cancer (NSCLC), downregulation of MTHFD2 expression suppresses the expression of cell cycle-related genes, such as CCNA2, MCM7, and SKP2." (PMID 35693982, 2022).
lung adenocarcinoma (17 papers, 2011 to 2024). A carcinoma that arises from the lung and is characterized by the presence of malignant glandular epithelial cells. "We found that overexpression of these 8 genes (CENPA, FAM83D, KNSTRN, CDKN3, CCNB1, CDK1, and CCNA2) is significantly associated with poor survival of lung adenocarcinoma patients (p-value < 0.05)." (PMID 36291764, 2022). "Data from the Gene Expression Omnibus (GEO) database shows that LINC00665 promotes lung adenocarcinoma by miR-let-7b-CCNA2." (PMID 35480884, 2022). "Our research demonstrates that CCNA2 and TGFB2 are potential diagnostic and prognostic biomarkers, as well as therapeutic targets in lung adenocarcinoma (LUAD)." (PMID 33195410, 2020). "Silencing of FOXM1 expression by siRNA in A549 lung adenocarcinoma cells resulted in significant reduction in cell cycle-promoting cyclin A2 and cyclin B1 genes, as well as DNA replication and mitosis." (PMID 31681566, 2019). "CCNA2 was found to be expressed in adenocarcinoma of lung and oral cancer cells." (PMID 37853361, 2023). "Platelet-related receptor genes based on multivariate Cox may be an important tool for diagnosing lung adenocarcinoma patients according to potential, and the ROC curve of CCNA2 is 0.970." (PMID 33619234, 2021). "Besides, CCNA2 is a Tanshinone IIA therapeutic target for inhibiting lung adenocarcinoma." (PMID 36419898, 2022).
endometrial cancer (15 papers, 2013 to 2025). Primary or metastatic malignant neoplasm involving the endometrium (mucous membrane that lines the endometrial cavity). "CCNA1 is restricted to the germ line, while CCNA2 is ubiquitously expressed in all proliferating cells and is upregulated in a variety of cancers including endometrial cancer." (PMID 39264721, 2024). "The CDC20 (50.25 ± 1.74 vs 23.67 ± 3.43, p < 0.01) and CCNA2 (46.65 ± 1.44 vs 24.67 ± 2.43, p < 0.01) shows significantly higher expression in endometrial cancer than cancer adjacent tissue." (PMID 31289358, 2019). "The gene function was evaluated by cell growth curve after knockdown CDC20 and CCNA2 of endometrial cancer cell line." (PMID 31289358, 2019). "We selected the two hub genes (CDC20 and CCNA2) that rarely been studied in endometrial cancer to evaluate gene expression values using IHC." (PMID 31289358, 2019). "Overexpression of CCNA2 was reported to be an indicator of a poor prognosis endometrial carcinoma." (PMID 25329664, 2014). "The expression of microRNA (miR)-524-5p reduced the migration and invasion of Ishikawa endometrial carcinoma (EC) cells, while decreasing BUB1, BUB1B, CCNA2, and CDCA8 expression." (PMID 37853361, 2023). "Our western blotting analysis demonstrated the accumulation of cyclin-A2 and -B1 in both the CPT- and AE-CA-treated cells, which indicated that the biological activity of AE-CA and CPT in human endometrial carcinoma cells is approximately equivalent." (PMID 24963324, 2014). "Interrogating Uterine Corpus Endometrial Carcinoma (TCGA-UCEC) and Uterine Carcinosarcoma (TCGA-UCS) cohorts revealed NCL to be the most highly upregulated gene in carcinosarcoma, with S100A11, LMNB2, RERG, E2F1 and CCNA2 representing key dysregulated NAGs in EC." (PMID 35682908, 2022).
glioblastoma (14 papers, 2008 to 2025). The most malignant astrocytic tumor (WHO grade IV). "Together, these data indicate that G. lucidum extract induced glioblastoma cells to arrest at S phase by inhibiting the expression of cyclin A2, cyclin D1, and CDK2." (PMID 32781747, 2020). "CCNA2 or Cyclin A, a member of the cyclin family, is not expressed in tumor cells but is a key gene of GASCs (Glioblastoma-Associated Stromal Cells), promoting glioblastoma growth and regulating the cell cycle." (PMID 40507925, 2025). "Therefore, from the data above we found that TBMS1 blocks glioblastoma cells in G2/M phase by inhibiting the expression of Cyclin A2, Cyclin B1, and CDK1." (PMID 31349699, 2019). "Top hub nodes from glioblastoma multiforme networks contain six matches, namely cyclin dependent kinase 2 (CDK2), cyclin A2 (CCNA2), cyclin B1 (CCNB1), erb-b2 receptor tyrosine kinase 2 (HER2), cyclin E1 (CCNE1), and cyclin D3 (CCND3)." (PMID 31952211, 2020).
osteosarcoma (14 papers, 2011 to 2024). A usually aggressive malignant bone-forming mesenchymal neoplasm, predominantly affecting adolescents and young adults. "However, in osteosarcoma cells, G1 cell cycle arrest was observed, and the expression of cyclin D1 and cyclin A2 was decreased due to Cdc6 deficiency." (PMID 33020506, 2020). "In another study, silencing CDC6 reduced CCNA2 expression and suppressed osteosarcoma cell proliferation and invasion." (PMID 33858425, 2021). "STIL is associated with osteosarcoma proliferation and invasion, and may be promote the progression of osteosarcoma by regulating the expression of CDK1, CCNB2, CDC20, CCNA2, BUB1 and AURKB." (PMID 33858425, 2021). "In the PPI network, we selected six genes (CDK1, CCNB2, CDC20, CCNA2, BUB1, and AURKB) as the core STIL differentially co-expressed genes in osteosarcoma." (PMID 33858425, 2021). "Using the 13 gene chips, we found that six hub differentially co-expressed genes (CDK1, CCNB2, CDC20, CCNA2, BUB1, and AURKB) were highly expressed in osteosarcoma." (PMID 33858425, 2021). "KIAA1429 may contribute to the progression of osteosarcoma by targeting CDK1, CCNA2, and CCNB2, which make it possible to become a potential biomarker and therapeutic target of osteosarcoma." (PMID 38164289, 2024). "Moreover, the bioinformatics analysis showed that STIL may participate in the biological function of osteosarcoma by regulating CDK1, CCNB2, CDC20, CCNA2, BUB1, and AURKB." (PMID 33858425, 2021).
leukemia (12 papers, 2012 to 2025). A malignant (clonal) hematologic disorder, involving hematopoietic stem cells and characterized by the presence of primitive or atypical myeloid or lymphoid cells in the bone marrow and the blood. "We utilized the data of gene expression profiling in samples with higher E2F1 expression and identified the genes associated with cell cycle progression (CCNA2, CCNE2, CCNB1, CCNB2 and, importantly, CCNE1) which were also found to be upregulated in leukemia cells exposed to DBF." (PMID 34564151, 2021). "Cyclin A2, which is ubiquitously expressed in dividing cells and plays role in DNA replication, entry into mitosis and spindle assembly, and cyclin A1, whose function is less clear and which is expressed in spermatocytes, leukemia cells and in postmitotic multiciliated cells." (PMID 32366979, 2020). "SRPK2 promoted the cell proliferation of leukemia by regulating cyclin A1 (not cyclin A2) expression." (PMID 31898732, 2020).
breast tumors (10 papers, 2002 to 2023). "Furthermore, our findings have shown that both Cyclin A2 and Ki-67 proliferation markers can be used for immune-histological identification of breast tumors with poor prognosis." (PMID 37273492, 2023). "Analysis of these miR-10b* targets by immunohistochemistry (IHC) in ten matched breast tumour and peritumoural tissues (from the cohort analysed by microarray miR profiling) showed remarkable increased staining of BUB1, PLK1 and CCNA2 in the tumour tissues." (PMID 23125021, 2012).
esophageal cancer (8 papers, 2012 to 2025). A primary or metastatic malignant neoplasm involving the esophagus. "Three hub targets were retrieved, including CENPF, CCNA2 (cyclin A), and CCNB1 (cyclin B1), which were highly expressed in esophageal cancer and associated with prognosis." (PMID 35484963, 2022). "A study on esophageal carcinoma showed that CCNA2 downregulation could enhance the antitumor effects of miR-219-5p." (PMID 40345591, 2025). "In the present study, we tried to describe the role of miR-29c-3p in esophageal carcinoma (EC) and the relationship of miR-29c-3p with CCNA2 as well as cell cycle, accordingly revealing the potential molecular mechanism across cell proliferation, migration and invasion." (PMID 32154226, 2020).